INS (insulin)
Diseases named in the same sentence as INS in open-access papers (continued):
Sharing a sentence is not in itself a finding about the gene and the disease.
Obesity (continued). "The present in vitro system provides insight into the metabolic changes of adipocytes under conditions of high glucose and insulin, which may help to understand the process of in vivo adipocyte hypertrophy during the development of obesity." (PMID 32618419, 2020). "The sub-group of insulin-sensitive individuals with obesity showing normal hormonal and metabolic profiles despite of their BMIs in obese category (i.e., ≥30 kg/m2) are classified as having “metabolically healthy obesity” (MHO)." (PMID 33511131, 2020). "Evidence suggests that obesity promotes CRC by activating the insulin/IGF-1 signaling pathway." (PMID 33346251, 2020). "In relation to insulin secretion, although fat in the exocrine pancreas is a poor marker of intra-islet fat accumulation, two studies found a correlation of increased pancreatic fat content during obesity, with declined ß-cell function." (PMID 32183037, 2020). "Additionally, Ship2-null mice are highly resistant to high-fat diet-induced obesity and exhibit increased insulin sensitivity and glucose tolerance, through increased insulin-induced activation of AKT in liver and muscle." (PMID 33276499, 2020). "The impact of the TT genotype, which appears to be a risk genotype for obesity, seems to not be related to carbohydrate intake, except for the associations with fasting insulin concentration and HOMA-IR level." (PMID 33114268, 2020). "Our finding of higher daily carbohydrate intake in the adult male offspring exposed to maternal pre-pregnancy overweight/obesity is noteworthy, as carbohydrates increase blood glucose levels, stimulating insulin release and accumulating fat tissue especially if consumed in high amounts." (PMID 32703940, 2020). "For example, due to the changes in insulin sensitivity that occur during pubertal development, an obesity onset in adolescence may be more deleterious for insulin resistance and diabetes than an onset during another period of the life course." (PMID 33290405, 2020). "Therefore, a number of therapeutic strategies against obesity have focused on reducing insulin/leptin resistance." (PMID 33218042, 2020). "Furthermore, an adipose-specific raptor knockout mouse was found to be lean and resistant to diet-induced obesity and have improved glucose tolerance and insulin sensitivity." (PMID 33024056, 2020). "Previous studies have reported that curcumin, black seed oil, and resveratrol have beneficial effects on insulin sensitivity and on the inhibition of inflammation Natural substances such as pomegranates may be beneficial towards combating obesity." (PMID 32751794, 2020). "Furthermore, BCAA, glutamine, glutamate, succinate, and several other metabolism products were increased as a time-depended factor during the 5 months dietary intervention and in relation to obesity development and rising levels of glucose and insulin." (PMID 33198236, 2020). "Gut microbes regulate insulin clearance during diet-induced obesity." (PMID 32860984, 2020). "Furthermore, dysfunctional lipid metabolism accompanies obesity and can negatively regulate insulin action." (PMID 33116232, 2020). "IL-4 is a Th2 cytokine that can promote M2 macrophage polarization in adipose tissues, and it has been proposed that IL-4 signaling could be a potential target to sustain insulin sensitivity in obesity." (PMID 32585823, 2020). "Genetic predisposition may be important in horses for the development of obesity and insulin dysregulation." (PMID 33302557, 2020). "In the frontal cortex, both prenatal stress and the HFD increased insulin levels; however, a decrease in the membrane glucose transporter (GLUT4) observed in the PS-R/HFD rats suggested weaker insulin action in the model of coexistence of depression and obesity." (PMID 31782099, 2020). "We hypothesized that the glucose-insulin axis in the first trimester of human pregnancy differs depending on maternal obesity status." (PMID 33154737, 2020).
Obesity (continued). "PINS’ role in the pathogenesis of the impaired insulin secretion in obesity is unclear." (PMID 31922022, 2020). "Visceral adipose tissue derived serine protease inhibitor (vaspin) is a member of the serpin family and has been shown to have beneficial effects on glucose tolerance, insulin stability as well as adipose tissue inflammation, parameters seriously affected by obesity." (PMID 32344508, 2020). "Overweight and obesity are conditions known to alter endothelial cell functionality through mechanisms such as insulin resistance, increased serum cholesterol and LDL levels, pro-inflammatory adipokine release and elevated free fatty acids (FFAs) production by adipose tissue." (PMID 32023876, 2020). "We and others have reported the increased adipose tissue IL-6 expression in obesity/T2D which could have consequences either as a circulating pleiotropic adipocytokine or as a local regulator of adipose inflammation and insulin action." (PMID 32188105, 2020). "A possible explanation for this observation could be several signals triggered by high insulin levels and obesity that promote proliferation, especially through the KRAS pathway." (PMID 33228173, 2020). "Finally, we aim to investigate if dapagliflozin treatment increases insulin and glucagon secretion in patients with obesity." (PMID 32059692, 2020). "Further investigation of hypothalamus-mediated insulin signaling following exposure to maternal HFHC-induced obesity at serial developmental time-points would further determine the role that hypothalamic IR plays in programming of obesity." (PMID 32987812, 2020). "Chronic low grade inflammation in obesity that may contribute to muscle wasting is regulated in part by adiponectin, leptin, and insulin controlling various inflammatory and anti-inflammatory processes." (PMID 33117276, 2020). "Liquid chromatography mass spectrometry–based untargeted plasma metabolomics was applied in 60 participants with obesity with a large range of peripheral insulin sensitivity as determined via a two‐step HIEC with stable isotopes [6,6‐2H2]glucose and [1,1,2,3,3‐2H5]glycerol." (PMID 32523723, 2020). "Bile acids, which are major intestinal metabolites, may have beneficial effects on obesity and hepatic insulin sensitivity." (PMID 32670255, 2020). "Children with obesity tend to have higher circulating blood insulin and leptin levels and may develop resistance to the actions of insulin and leptin." (PMID 33266497, 2020). "Men are also more likely to suffer from obesity and effects of sedentary lifestyle than women, probably due to differences in insulin sensitivity and regional fat storage, which may be due to disrupted sex hormone homeostasis." (PMID 32290381, 2020). "BMS leads to a remission/resolution of T2D, improving glycemic control, insulin sensitivity, hyperlipidemia, and other obesity-associated disorders, but its precise mechanisms are not yet fully understood." (PMID 33142938, 2020). "In addition to the miRNAs, recently, lncRNAs also gained importance in obesity research as key regulators of adipogenesis, inflammation, and insulin sensitivity." (PMID 32594318, 2020). "Taken together, our data suggest a role of Hoxc9 in the development of obesity and the determination of fat depot-specific signatures, which may affect whole body glucose metabolism, insulin sensitivity, and energy expenditure." (PMID 32610701, 2020). "In obesity, adipocytes may become hypertrophy, hypoxia or death, which can result in severe dysfunction of adipose tissue (AT) and impairment of insulin sensitivity." (PMID 32580621, 2020). "This includes obesity (regional and/or generalized) and systemic insulin dysregulation/resistance." (PMID 33302557, 2020). "Thus, adipose-specific deletion of TBK1 (ATKO) attenuates diet-induced obesity with exacerbation in glucose intolerance and insulin resistance, whereas genetic deletion of IKKε increases energy expenditure with improvement in insulin sensitivity on a HFD34,35." (PMID 33168920, 2020).
Obesity (continued). "Hence, in the present cross-sectional study we aimed to analyse the influence of maternal obesity on the glucose-insulin axis in the first trimester of human pregnancy spanning the range of week 4+0 to 11+6." (PMID 33154737, 2020). "Although evidence of differential regulation of insulin signalling pathway based on nutritional stimulations is available, molecular mechanisms responsible for insulin resistance and obesity heterogeneity are largely speculative at this time." (PMID 32670384, 2020). "A high-fat diet is accompanied by obesity, insulin resistance and oxidative stress." (PMID 32172503, 2020). "Similarly, in boys with obesity, there was a higher expression of insulin (p <0.0001), leptin (p <0.0001), c-peptide (p < 0.0001), amylin (p = 0.0013), glucagon (p = 0.04), GLP-1 (p < 0.0001), and ghrelin (p = 0.07), compared to the eutrophic group." (PMID 33644105, 2020). "Therefore, increased plasma SPARC in patients with obesity would play a role in induction of insulin secretion." (PMID 33067534, 2020). "Although that study suggested that the relationship between IPFD and insulin sensitivity might play a role in the pathogenesis of NODAP, it is possible that general obesity confounded the observed association in individuals with NODAP." (PMID 32967240, 2020). "The microbes from the HFD-fed mice were contributors to impaired insulin clearance during obesity." (PMID 32860984, 2020). "Further studies are needed to elucidate whether and how obesity may amplify the effects of excess added sugar intake on insulin action." (PMID 33228087, 2020). "Moreover, further studies are required to determine the effects of obesity-related circulating exosomes on insulin signaling pathways in other cells such as primary hepatocytes, skeletal muscle cells, adipocytes, and immune cells." (PMID 32322309, 2020). "However, alterations in PL develop in obesity where vital metabolic molecules become dysregulated, such as adiponectin, an adipose tissue-derived adipokine that contributes to insulin sensitivity and regulates glucose metabolism." (PMID 33333828, 2020). "Adiponectin serves as a protective factor to prevent obesity occurrence and/or progression by suppressing inflammation, promoting fatty acid oxidation, and improving insulin sensitivity, while resistin is important in maintaining homeostasis of insulin action, energy, glucose, and lipids." (PMID 32586265, 2020). "Therefore, further studies would be necessary to know if β-cell dysfunction in the smaller clusters drives hyperglycemia and impairs insulin secretion during obesity." (PMID 33353164, 2020). "Moreover, RSV-treated mice at a dose of 4 g/kg increased their exercise capacity, oxygen consumption, and improved insulin sensitivity against high-fat induced obesity." (PMID 32848876, 2020). "Obesity-induced synovial inflammation, chondrocyte hypertrophy, and meniscal mineralization are mitigated through oligofructose, a non-digestible prebiotic fiber that facilitates the expansion of beneficial Bifidobacteria and improves insulin resistance." (PMID 32431699, 2020). "Therefore, research is currently directed toward targeting inflammatory signals in obesity to restore insulin sensitivity and improves glucose homeostasis." (PMID 31973745, 2020). "Strategies such as blocking expression of MKP-1 in skeletal muscle with antisense oligonucleotides could be beneficial in improving insulin sensitivity and prevent the development of obesity." (PMID 33179019, 2020). "Mice deficient in CB1 displayed no changes in glucose tolerance and insulin sensitivity in association with diet-induced obesity." (PMID 32365865, 2020). "The increase of lipolysis driven by cAMP intracellular level, may be one of the factors contributing to obesity-related insulin resistance controlled by PGE2 receptors in visceral adipose tissue." (PMID 31947646, 2020). "We investigated whether MCR protects brain function through insulin signaling in an HFD mouse model of obesity." (PMID 32575897, 2020).
Obesity (continued). "However, insulin was significantly higher in children with obesity than in the standard weight group." (PMID 33292260, 2020). "Moreover, in the mitochondria of individuals suffering from obesity and type 2 diabetes, ATP synthesis is reduced, which correlates with the accumulation of FFAs and inhibition of insulin-stimulated glucose utilization." (PMID 32963827, 2020). "In addition, obesity development is often paralleled by a decrease of whole body insulin sensitivity characterized by increased plasma levels of glucose and insulin, which is ascribed to the limits of AT expandability accompanied by ectopic lipid deposition." (PMID 32618419, 2020). "This relationship may reflect the underlying relationship between maternal BMI and both human milk insulin concentrations, and milk fat, as several studies have reported that women with higher BMI and/or obesity produce milk with higher fat content." (PMID 33123548, 2020). "Adiponectin plays an important role in anti-inflammatoryprocesses, insulin sensitivity and obesity." (PMID 32112632, 2020). "Taken together, our observations that insulin enhances adipocyte mitochondrial coupling, while ketones drive uncoupling, may provide insight into obesity etiology." (PMID 32872407, 2020). "Although it is not fully understood, some of the mechanisms postulated to explain metabolically healthy obesity include preserved insulin sensitivity, a higher fat accumulation in SAT than in visceral and ectopic depots, normal adipose tissue function, and normal adipokine secretion." (PMID 33081064, 2020). "For example, reduced sensitivity to insulin is seen in some DMD and Becker muscular dystrophy human patients, and insulin-related metabolic disorders (e.g., hyperinsulinemia, glucose intolerance, obesity) are seen in muscular dystrophies such as myotonic dystrophy type 1 and 249–51." (PMID 32170063, 2020). "Since hyperinsulinemia and increased bioavailability of insulin-like growth factors (IGFs) are typically associated with insulin resistance in patients with T2DM and obesity, researchers have long considered a pivotal role of insulin/IGF signaling in tumors, including PC." (PMID 32659999, 2020). "Moreover, adipose-derived POA levels remain strongly elevated in a models that remains insulin sensitive despite developing diet-induced obesity." (PMID 32738301, 2020). "The purpose of this brief review is to highlight recent studies that have explored whether the sexual dimorphism in obesity-induced sympathoexcitation is due to sex differences in the actions of two metabolic hormones, leptin and insulin." (PMID 32160920, 2020). "Thus, this review describes the role played by S1P metabolism in the development of obesity/T2D by analysing the enzymes regulating both its tissue and circulating levels in insulin resistance of peripheral tissues and pancreatic β cell fate." (PMID 32668665, 2020). "It is reasonable to assume that regulating CARKL may reduce obesity-induced inflammation, leading to increased insulin sensitivity." (PMID 32582032, 2020). "It is known that this retinoid is able to ameliorate the negative effects associated with obesity, improving different processes, such as glucose tolerance, insulin sensitivity, and serum lipid profile." (PMID 32751185, 2020). "Furthermore, previous studies of human subjects with different types and degrees of obesity have revealed a direct correlation between autophagic activity and insulin sensitivity." (PMID 33320092, 2020). "Obesity caused by a high-fat diet (HFD) has also been related to the release of pro-inflammatory cytokines in the hypothalamus and hippocampus, leading to leptin and insulin insensitivity and cognitive impairment." (PMID 33322180, 2020). "As a speculation, early dysregulation in the glucose-insulin axis may link maternal obesity/fat mass with altered placental development and contribute to adverse pregnancy outcomes in obese mothers." (PMID 33154737, 2020).
Obesity (continued). "However, previous studies have shown that ANGPTL3 levels are abnormally increased in insulin-resistant state and obesity, with worsening glucose metabolism and enhancing lipolysis in adipose tissues." (PMID 33273510, 2020). "Obesity exerts detrimental effects on lipid metabolism, such as TC, TG and insulin production." (PMID 33042284, 2020). "However, microbes identified in clusters 2 and 3, which were phylogenetically similar, were potential candidates for driving defective insulin clearance during diet-induced obesity." (PMID 32860984, 2020). "There was no observed association between markers of obesity (BMI, insulin, leptin, and CRP), serum 25-OH vitamin D levels and estradiol or estrone levels." (PMID 32566743, 2020). "As expected, obesity in Zucker (fa/fa) rats was accompanied by an increase in plasma insulin, C-peptide 2, triglycerides, cholesterol and LDL/HDL ratio, decreased insulin sensitivity index (QUICKI) and plasma oxytocin level without significant changes in fasting glycemia." (PMID 33344504, 2020). "Since changes in the dynamic properties of the cell membrane could be one of the events by which obesity affects insulin sensitivity, the importance of cell membrane lipids as essential regulators of insulin resistance has been considered." (PMID 32899471, 2020). "The liver is a major insulin target organ, is the main source of endogenous glucose production, plays a chief role in the control of systemic lipid metabolism, and is central to the link between obesity and type-2 diabetes." (PMID 32694512, 2020). "Exposing offspring to a postnatal HF diet in addition to maternal HF feeding further exacerbates metabolic abnormalities, resulting in obesity, increased food intake, steatohepatitis, inflammation, hyperglycemia, and impaired insulin signaling in central and peripheral tissues." (PMID 31947955, 2020). "In fact, gram-negative bacteria are known to produce lipopolysaccharides (LPS), which may induce inflammation, insulin resistance, and obesity by leaking into the blood-stream." (PMID 32552864, 2020). "Since the classical monocytes have upregulated chemokines such as CCR2 and CCR5 it is likely that this contributes to more activated tissue macrophages in the children with obesity in this cohort, and why these same children with obesity have higher insulin levels and HOMA-IR." (PMID 32528415, 2020). "A larger follow-up study by the same group once again demonstrated a statistically significant increase in peripheral insulin sensitivity among 26 adults with obesity receiving endoscopic FMT infusion from lean donors, although the magnitude of improvement was more modest (approximately 12%)." (PMID 32150549, 2020). "In a brain-specific reduced ER stress mouse model, severe leptin resistance significantly increased obesity on a high-fat diet, which suggested that ER stress might participate in the adjustment of insulin sensitivity in brain." (PMID 32375323, 2020). "Overweight and obesity are generally considered to be the risk factors for PTB due to the effects of placental insufficiency, inflammatory state, insulin sensitivity and cellular oxidative stress." (PMID 33088625, 2020). "For instance, inactivation of EST, the enzyme responsible for oestrogen deactivation, increases energy expenditure, improves insulin sensitivity, and reduces hepatic gluconeogenesis and lipogenesis in different mouse models of obesity-related metabolic disorders, but only in females." (PMID 31754750, 2020). "Area covered: Here, we review the currently available studies characterizing the mitochondrial proteome in human skeletal muscle in insulin-resistant conditions, such as obesity, T2D, and aging, as well as exercise-mediated changes in the mitochondrial proteome." (PMID 32731645, 2020).